MMP14 (matrix metallopeptidase 14)
Diseases named in the same sentence as MMP14 in open-access papers (continued):
Sharing a sentence is not in itself a finding about the gene and the disease.
clear cell carcinomas (2 papers, 2016 to 2021). "A case of clear-cell carcinoma shows intense expression for MMP-14 (1c) and less intense expression for MMP-2 (1d)." (PMID 27038607, 2016). "Only one patient with a clear-cell carcinoma had both epithelial and stromal MMP-14 and MMP-2 expression." (PMID 27038607, 2016). "A study from Japan confirmed high MMP-14 expression in 22/30 clear cell carcinomas, while only 1/30 serous carcinomas was positive without correlation with stage or survival." (PMID 34344453, 2021). "Six other patients with a clear-cell carcinoma showed epithelial MMP-14 staining of which two had no stromal MMP-14 staining." (PMID 27038607, 2016). "In our cohort, MMP-14 and MMP-2 expression are not confined to clear-cell carcinomas, and not all clear-cell carcinomas express both proteins." (PMID 27038607, 2016). "Nor epithelial MMP-14 and MMP-2 expression, nor stromal MMP-14 and MMP-2 expression was related to stage or survival in these seven patients with a clear-cell carcinoma." (PMID 27038607, 2016).
cleft palate (2 papers, 2010 to 2019). Cleft palate is a fissure type embryopathy that affects the soft and hard palate to varying degrees. "Interestingly, combined double knockout of Mmp14 and Mmp16 in mice leads to severe structural and craniofacial defects, including severe dysfunction in palatal shelf formation and cleft palate in 80% of the embryos." (PMID 31921852, 2019). "While MMP and TIMP expressions appear to be critical throughout all stages of palatal development, knockout mice for Timp1, Timp2, Timp3, Timp4, Mmp2, Mmp9, Mmp13, Mmp14, Mmp16, and Mmp25 do not develop cleft palate." (PMID 31921852, 2019).
colorectal adenocarcinoma (2 papers, 2022 to 2025). The most common type of colorectal carcinoma. "The impact of MMP14 on colorectal adenocarcinoma (COAD) was investigated by analyzing OS and PFS in TCGA-COAD cohorts with varying expression levels." (PMID 40352589, 2025).
Crohn disease (2 papers, 2020 to 2021). A gastrointestinal disorder characterized by chronic inflammation involving all layers of the intestinal wall, noncaseating granulomas affecting the intestinal wall and regional lymph nodes, and transmural fibrosis. "Regarding the inflamed tissue of IBD patients, Crohn’s disease (CD) patients with CRC development showed a higher expression of MMP-14 by fibroblasts and by mononuclear inflammatory cells (MICs) than CD patients without CRC development." (PMID 33946534, 2021).
Diabetes Mellitus Type II (2 papers, 2022 to 2025). "Consequently, the expression of MMP-3 and MMP-14 may be valuable as markers for periodontal inflammation in individuals with type 2 diabetes." (PMID 40075856, 2025). "Moreover, the study found that MMP-14 and TIMP-1 expression levels were elevated in inflamed gingival tissue, suggesting that PGE2 and MMP-14 may contribute to the process of alveolar bone resorption and the progression of periodontal inflammation associated with type 2 diabetes." (PMID 40075856, 2025).
diffuse large B-cell lymphoma (2 papers, 2020 to 2021). "However, the correlation between MMP14 expression, prognosis, and immune cell infiltration in diffuse large B-cell lymphoma (DLBCL) remains unclear." (PMID 32974187, 2020).
Dupuytren’s disease (2 papers, 2021). "Other potential causal genes at associated loci included MMP14, a missense variant previously finemapped for Dupuytren’s disease, and SFRP4." (PMID 34111113, 2021).
endotoxemia (2 papers, 2020 to 2026). "Consistently, MMP14 blockade profoundly reduced pulmonary Gr-1 neutrophil infiltration in LPS-induced endotoxemia in mice." (PMID 32838837, 2020).
gastric tumors (2 papers, 2014). "For this reason, it has been suggested that MMP-14 participates in the invasion of gastric tumors and could therefore be utilized as a molecular marker for this disease." (PMID 24669030, 2014).
Glucose intolerance (2 papers, 2022 to 2024). Glucose intolerance (GI) can be defined as dysglycemia that comprises both prediabetes and diabetes. "We show that hepatocyte MMP14 drives diet-induced injury, which includes peripheral adiposity, glucose intolerance, hepatic triglyceride (TG) accumulation, and inflammatory and fibrotic gene expression." (PMID 39282008, 2024).
Granuloma (2 papers, 2014 to 2015). A compact, organized collection of mature mononuclear phagocytes, which may be but is not necessarily accompanied by accessory features such as necrosis. "Clearly, the absence of T and B lymphocytes had little impact on extent of MMP-13 or MMP-14 staining, consistent with the PCR data obtained from granuloma FCMs." (PMID 25389425, 2014).
hearing loss (2 papers, 2020 to 2023). "Together, our data motivate further evaluation of the roles other MMPs, in particular MMP-2 and MMP-9, play in interacting with MMP-14 to promote VS growth and development of associated hearing loss in larger datasets." (PMID 32848608, 2020). "It is suggested that the expression of MMP-14 is not closely related to hearing impairment." (PMID 37904429, 2023).
intestinal cancer (2 papers, 2018 to 2023). "Besides PGK1, which we described in the results part, another unfavorable prognostic gene MMP14 conferred chemoresistance in the APCMin-mouse model of intestinal cancer." (PMID 37654625, 2023). "Serum MMP-14 served as a strong prognostic factor in patients with an intestinal cancer." (PMID 30532247, 2018).
ischemia (2 papers, 2018 to 2020). A hypoperfusion of the BLOOD through an organ or tissue caused by a PATHOLOGIC CONSTRICTION or obstruction of its BLOOD VESSELS, or an absence of BLOOD CIRCULATION. "Studies in a model of liver ischemia–reperfusion injury have indicated a role for MMP-14 in facilitating macrophage infiltration into the injured liver via interactions with fibronectin." (PMID 32296422, 2020).
liver cirrhosis (2 papers, 2020 to 2021). "Recently we described, that increased expression of the proteoglycan triggers the synthesis of MMP-14, a protease playing critical role in matrix degradation, hindering this way the development of liver cirrhosis in experimental system." (PMID 30826971, 2020).
lung squamous cell carcinoma (2 papers, 2021 to 2022). "Matrix metalloproteinase 14 (MMP14) was found to be another target of miR-150-5p in squamous cell lung cancer tissue biopsies." (PMID 36613642, 2022). "High MMP14 expression predicted a poor prognosis of lung squamous cell carcinoma (LUSC) patients." (PMID 34868395, 2021).
muscular dystrophies (2 papers, 2020 to 2025). "Both MMP2 and MMP14 have been shown to promote adipogenesis in adipose tissue, skeletal muscle, and FAPs and are implicated in the pathogenesis of several muscular dystrophies, including Duchenne, Emery-Dreifuss, and congenital muscular dystrophy 1D." (PMID 40966415, 2025).
Pleural effusion (2 papers, 2012 to 2021). The presence of an excessive amount of fluid in the pleural cavity. "Serum MMP-14 was determined in a small series of fluids (cystic, ascites and pleural effusions) from 14 patients, 10 of them being malignant and demonstrating a threefold increase compared to benign fluids." (PMID 34344453, 2021).
rhabdomyosarcoma (2 papers, 2019 to 2025). A rare aggressive malignant mesenchymal neoplasm arising from skeletal muscle. "Moreover, the low MMP14 expression of alveolar rhabdomyosarcomas and the epithelial characteristics of epithelioid sarcomas is consistent with their preference for utilizing the lymphogenous route." (PMID 31466240, 2019). "For instance, the more aggressive alveolar rhabdomyosarcoma presents higher protein levels of both MMP14 and MMP2 than the embryonal rhabdomyosarcoma type, where both these proteases are often undetectable." (PMID 31466240, 2019).
schwannoma (2 papers, 2020 to 2025). A benign, usually encapsulated slow growing tumor composed of Schwann cells. "In VS that underwent subtotal resection, there was an elevated expression and secretion of MMP‐14 by schwannoma cells." (PMID 39506612, 2025). "Having established that MMP-14 is significantly overexpressed in both a schwannoma cell line and primary VS tumor culture, we next investigated the in vivo pattern of MMP-14 expression in formalin-fixed, paraffin-embedded tumor specimens from patients with VS as well as in GAN control sections." (PMID 32848608, 2020).
serous carcinoma (2 papers, 2016 to 2021). "Clearly, the stroma of a serous carcinoma stains positive for MMP-14 (1a) and negative for MMP-2 (1b)." (PMID 27038607, 2016).
tongue squamous cell carcinoma (2 papers, 2014 to 2023). A squamous cell carcinoma that arises from the tongue. "Previous studies have also shown that MMP14 is highly expressed in tongue squamous cell carcinoma (TSCC) and that this protein may be a target for reducing migration and invasion in TSCC via its regulation of miR-34a, a well-known tumor suppressor gene." (PMID 36820030, 2023).
tuberculosis (2 papers, 2015 to 2018). A chronic, recurrent infection caused by the bacterium Mycobacterium tuberculosis. "MMP proteins have been linked to leukocyte migration and the progression of granuloma formation during tuberculosis; MMP1 and MMP14 gene products are key for the destruction of collagen and alveolar destruction with increased expression of MMP14 found in the sputum of tuberculosis patients." (PMID 29343690, 2018).
vasculitis (2 papers, 2020 to 2021). "Macrophage-induced MMP-2, MMP-9, and MMP-14 (MT1-MMP) enzymatic activity facilitates infiltration and degradation of collagen in the basement membrane for a number of diseases, including fibrosis, vasculitis, and dermatitis." (PMID 34527702, 2021).
Abdominal obesity (1 paper, 2021). Excessive fat around the stomach and abdomen. "The strength of the association between high levels of MMP-14 and CVD was similar to the strengths of the associations between abdominal obesity, depression and CVD." (PMID 34702365, 2021). "Depression, abdominal obesity and high MMP-14 levels were independently and to an almost equal degree associated with CVD." (PMID 34702365, 2021).
adolescent idiopathic scoliosis (1 paper, 2024). A scoliosis with no known cause arising in adolescent. "(A) A heatmap of transcript per million (TPM) values of COL11A1, MMP14, and other published genes associated with adolescent idiopathic scoliosis (AIS)." (PMID 38277211, 2024).
bacterial pneumonia (1 paper, 2022). Acute infection of the lung parenchyma caused by bacteria (e.g., Streptococcus pneumoniae, Haemophilus influenzae, Chlamydia pneumoniae, Mycoplasma pneumoniae, and Legionella pneumophila). "MMP-14 mediated breakdown of the ECM in IAV infection has shown to increase susceptibility to bacterial pneumonia in mice." (PMID 35512020, 2022).
basal cell carcinoma (1 paper, 2026). A carcinoma involving the basal cells. "In Basal cell carcinoma, the significant expression of MMP-3 and MMP-14 suggests involvement in local proliferation and stromal remodeling rather than high metastatic capacity." (PMID 42158425, 2026).
biliary atresia (1 paper, 2016). A rare, biliary tract disease characterized by progressive obliterative cholangiopathy of the intra- and extrahepatic bile ducts, occurring in the embryonic/ perinatal period, leading to severe and persistent neonatal jaundice and acholic stool. "Interestingly, dysregulation of MMP14 has also been reported in both human and animal models of biliary atresia." (PMID 27139180, 2016). "This suggests that the activation of TGFβ in the setting of biliary atresia may in part be mediated through both increased αvβ8 expression and altered expression of MMP14." (PMID 27139180, 2016).
cervical squamous cell carcinoma (1 paper, 2021). A squamous cell carcinoma arising from the cervical epithelium. "In research on tissue of uterus obtained during hysterectomy in patients with cervical squamous cell carcinoma, the expression of membrane-bound matrix metalloproteinase MT1-MMP (MMP-14), its tissue inhibitor TIMP-2, and its activator proMMP-14 furin was investigated." (PMID 34830452, 2021).
cholangiocarcinoma (1 paper, 2025). A carcinoma that arises from the intrahepatic biliary tree (intrahepatic cholangiocarcinoma) or from the junction, or adjacent to the junction, of the right and left hepatic ducts (hilar cholangiocarcinoma). "Furthermore, the expression of MMP14 in cholangiocarcinoma tissue is significantly elevated compared to adjacent tissues." (PMID 40070825, 2025). "I-FLICE, MUC1, MMP14, mIDH1, and SPP1 were found to be highly expressed in cholangiocarcinoma tissues, and they promoted cholangiocarcinoma progression by affecting T cell interactions or T cell immune infiltration." (PMID 40070825, 2025).
cholesteatoma (1 paper, 2023). A pathologic process characterized by the proliferation of keratinizing squamous epithelium resulting in the accumulation of keratin and cells in the middle ear and/or mastoid. "The difference in MMP-14 expression in cholesteatoma tissue and normal skin of the external auditory canal was detected using an immunohistochemistry technique in this study." (PMID 37904429, 2023). "The distribution of MMP-14 in cholesteatoma tissue and external auditory canal epithelium was statistically significant, according to the data." (PMID 37904429, 2023). "According to the findings of this study MMP-14 was found in all layers of the cholesteatoma epithelium with the strongest expression in the basal layer and the adjacent spinous layer." (PMID 37904429, 2023). "Expression of MMP-14 in cholesteatoma of different age groups." (PMID 37904429, 2023). "Expression of MMP-14 in cholesteatoma and normal external auditory canal." (PMID 37904429, 2023). "Our study showed the expression of MMP-14 in cholesteatoma epithelium was significantly higher than that in normal external auditory canal epithelium which indicated MMP-14 might play an important role in the pathological development of cholesteatoma." (PMID 37904429, 2023). "Expression of MMP-14 in cholesteatoma of different gender groups." (PMID 37904429, 2023). "Increased activity of MMP-14 has been demonstrated in cholesteatoma tissue; however, the underlying molecular mechanism has not been investigated in detail." (PMID 37904429, 2023).
chronic hepatitis B (1 paper, 2021). "This was similar to the role of MMP-9 in chronic hepatitis B patients and in oral keratinocytes, as well as MMP-14 in NSCLC patients." (PMID 33593275, 2021).
co-infection (1 paper, 2023). "Furthermore, when the researchers used a second mouse model of co-infection of IV with S. pneumoniae, they found that treatment with the specific MMP-14 inhibitor antibody significantly improved the survival of co-infected mice, compared to the bacteria-only infected control." (PMID 37727782, 2023).
Cognitive impairment (1 paper, 2025). Abnormal cognition is characterized by deficits in thinking, reasoning, or remembering. "This dynamic upregulation of MMP-14 in both murine models and human disease highlights its potential role as a mediator of neurodegeneration and cognitive impairment under both physiological and pathological conditions." (PMID 40983624, 2025). "However, the damaging effects of aged plasma on cognition were absent in 2-month-old young Mmp14+/− mice, suggesting that MT1-MMP serves as a key mediator linking systemic aging signals to hippocampal dysfunction and cognitive impairment." (PMID 40983624, 2025).
cystic fibrosis (1 paper, 2020). Autosomal recessive disorder caused by pathogenic variants in the CFTR gene (cystic fibrosis transmembrane conductance regulator), which encodes a chloride and bicarbonate channel expressed in epithelial cells, and follow the diagnosis criteria. "Given the importance of the proper regulation of plasma membrane levels of E-cadherin and MMP14 in cancer and of CFTR in cystic fibrosis, it is essential to identify the molecular pathways that control their trafficking." (PMID 32344433, 2020).
delirium (1 paper, 2023). A disorder characterized by confusion; inattentiveness; disorientation; illusions; hallucinations; agitation; and in some instances autonomic nervous system overactivity. "We observe decreased levels in three proteases (CTSV, CTSD and MMP14) in the CSF of patients that will develop delirium." (PMID 37759795, 2023).
dementia (1 paper, 2021). Loss of intellectual abilities interfering with an individual's social and occupational functions. "We found that fewer severity-related F-ADGs were found in the all sample group, GNAQ and MMP14, while more severity-related genes appeared in the mild or moderate dementia subgroup." (PMID 33603656, 2021).
dengue (1 paper, 2025). "In deeper understanding of dengue pathogenesis, it becomes the obvious question whether NS1 antigen alone or other MMPs like MMP-14 might have some adverse effects on lung epithelial cells." (PMID 41459161, 2025).
depression (1 paper, 2021). "None of the traditional risk factors for CVD such as low grade inflammation (increased CRP), increased HbA1c, dyslipidaemia, increased blood pressure, physical inactivity, smoking, or the less established risk factor—depression, was associated with MMP-14." (PMID 34702365, 2021). "The main aim was to explore theQuery associations between MMP-14 and selected inflammatory and metabolic variables, CVD, depression, physical activity, smoking, and medication, in patients with T1D." (PMID 34702365, 2021). "The main aim was to explore the associations between MMP-14 and selected inflammatory and metabolic variables, CVD, depression, physical activity, smoking and medication in patients with T1D." (PMID 34702365, 2021). "We explored and adjusted for relevant variables previously linked to CVD: MMP-2, MMP-9, MMP-14, TIMPS, galectin-3, CRP, metabolic variables, life style variables, depression, and thyroid disease." (PMID 34702365, 2021).
dermatitis (1 paper, 2021). An inflammatory process affecting the skin. "MMP-14 has also been shown to be involved in macrophage infiltration in a murine model of contact dermatitis, where in Mmp-14−/− mice showed reduced macrophage infiltration at the site of dermatitis." (PMID 34527702, 2021).
diabetic foot ulcers (1 paper, 2025). "Chronic, non-healing diabetic foot ulcers and pressure ulcers are associated with higher levels of MMP9 and/or MMP14 than healed ulcers." (PMID 39882906, 2025).
Diabetic Nephropathy (1 paper, 2023). "Predicted gene #10, MMP14, is a member of the matrix metallopeptidase/metalloproteinase family that is well established to have a role in Diabetic Nephropathy." (PMID 36791052, 2023).
digestive system carcinoma (1 paper, 2020). A malignant neoplasm that arises from the epithelium of any part of the digestive system. "However, there is no comprehensive quantitative evaluation of the MMP-14 prognostic value in digestive system carcinoma (DSC)." (PMID 31956360, 2020).
E. coli infection (1 paper, 2020). "The expression of these proteases remained unchanged after EPS pretreatment prior to E. coli infection, except MMP14 (logFC of 2.47)." (PMID 32234079, 2020). "E. coli infection resulted in the upregulation of the genes encoding proteases, which participate in the degradation of ECM, namely, ADAM10 (logFC of 2.62), ADAM17 (logFC of 8.75), MMP9 and MMP14 (both with a logFC of 2.58), CAPN7 and CAST (both with logFC of 2.20)." (PMID 32234079, 2020).
Endocrine Pancreatic Cancer (1 paper, 2019). "About the studies of rs2236302 on MMP‐14 gene, we found that it has been done in some relevant researches among Endocrine Pancreatic Cancer, squamous cell neoplasia of uterine cervix, and early onset of esophageal adenocarcinoma." (PMID 30548828, 2019).